CTLA4 (cytotoxic T-lymphocyte associated protein 4)
Diseases named in the same sentence as CTLA4 in open-access papers (continued):
Sharing a sentence is not in itself a finding about the gene and the disease.
tumor (continued). "Used as monotherapy, neither ICB (anti-PD-1 and anti-CTLA-4) nor activating antibodies (anti-OX40 and anti-CD137) had any significant impact on ID8 tumor-bearing mouse survival, possibly due to the compensatory upregulation of additional checkpoints on T-cells, such as LAG-3." (PMID 32630708, 2020). "In addition, we found that tumor-infiltrating CD25+ T cell express TIM-3 at significantly higher levels than CD25− TILs and also co-express CTLA-4 and PD-1, but do not express LAG-3." (PMID 32041340, 2020). "Moreover, anti‐CTLA4 antibody promoted NSCLC cell proliferation in vitro and tumour growth in vivo in the absence of adaptive immunity." (PMID 30378264, 2019). "In mouse models, anti-CTLA-4 mAbs do not block CTLA-4-B7 interaction, yet they remain active in anti-tumor efficacy, suggesting that intratumoral depletion of Tregs by anti-CTLA-4 antibodies might be the primary MOA." (PMID 30863404, 2019). "Likewise, tumor-bearing mice also expressed higher levels of cell surface CTLA-4 than naïve mice, allowing us to reveal downregulation of CTLA-4 by Ipilimumab in the absence of anti-PD-1 treatment." (PMID 31267017, 2019). "Second, many other factors such as IFN-γ+ Th1 response, CTLA-4, and LAG3-mediated effector T cell exhaustion are all involved in Treg-mediated tumor immune escape, which means that it is not possible to completely exclude the interference of other confounding factors on the results." (PMID 31930120, 2019). "In another study combining anti-CTLA-4 therapy with ablation, anti-viral responses were again seen in HCV+ patients and those patients who did not have an anti-viral response also did not benefit in terms of tumor control." (PMID 31627733, 2019). "Although CD8+ T-cells in the tumor were activated and expanded to a greater or lesser extent by these therapies, tumor growth suppression was achieved only by anti-PD-1, anti-PD-1/4-1BB combined, or by anti-CD4 treatment, but not by anti-CTLA-4 or anti-4-1BB monotherapy." (PMID 29348598, 2018). "Due to the heterogeneity of CTLA-4 expression, the reaction on a very small size TMA sample may not be representative of the entire tumor." (PMID 29672601, 2018). "This prompted us to assess whether CTLA-4 blocking also affects the magnitude of those antigen-specific CD8+ T cells in spleens, draining and non-draining lymph nodes of tumour-bearing mice." (PMID 28916749, 2017). "However, the particular tumor model employed is likely important, as the anti-CD20/CTLA-4 combination is not effective in all models (unpublished data)." (PMID 29046676, 2017). "In marked contrast, surgical removal of first tumours plus two rounds of anti-CTLA4 treatment (pre and post), or even anti-CTLA4 (pre and post) in combined with s.c. injected PLGA-ICG-R837, exerted no appreciable inhibitory effect to the rechallenged tumours." (PMID 27767031, 2016). "However, cells lacking CTLA-4 were unable to control proliferation of target cells stimulated by anti-CD3 antibody and DC, and to induce tumor rejection." (PMID 26870040, 2016). "However, α-CD137 combined with α-PD-1 antibodies significantly enhanced the anti-tumor effect of SBRT, while the anti-tumor effect of SBRT was not enhanced by interleukin-2, or the combination of α-CTLA-4 and α-PD-1." (PMID 27160390, 2016). "Preliminary results from another phase I trial combining durvalumab (anti-PD-L1) and tremelimumab (anti-CTLA-4) in NSCLC patients showed an overall response rate of 25 %, and the interesting finding that this efficacy did not depend on PD-L1 expression in the tumor." (PMID 31093342, 2016). "In addition, tumor burden at the time of intervention with immunotherapy and radiation may influence outcome since patients with a significant metastatic burden did not benefit from a combined approach of CTLA-4 blockade and RT, whereas limited disease burden correlated with improved survival." (PMID 27660705, 2016).
tumor (continued). "No expression of CTNNB1, CTLA4, EPCAM, ERBB2, MET, p40, PD-L1 and SOX2 could be detected in any of the tumors, PD-L1 was negative in tumor as well as stromal cells." (PMID 26943575, 2016). "Tumor CD4+ T cell infiltration was not significantly altered by either gemcitabine or anti-CTLA-4, although ICOS expression as a marker of activation was decreased in all gemcitabine-treated mice, either with or without anti-CTLA4." (PMID 23626745, 2013). "Combination regimens involving PD-1/PD-L1 inhibitors and CTLA-4 inhibitors have demonstrated superior clinical efficacy compared to monotherapy in multiple randomized trials—including POSEIDON, CheckMate 227, and CheckMate 032—regardless of tumor histology or PD-L1 expression levels." (PMID 40777022, 2025). "In addition, the combination of hIL-7/mIL-12-VV with anti-PD-L1 or CTLA4 antibodies showed a stronger antitumor effect in CT26 models, with complete regression in almost all mice without indications of cytokine storm despite the extent of tumor regression." (PMID 39451566, 2024). "Thus, in Treg-dominant tumors, CTLA-4 blockade may preferentially support Treg expansion and not improve CTL-based tumor control, regardless of the RT regimen used." (PMID 38349740, 2024). "Given that previous studies have observed complementary activity of PD-L1 and CTLA-4 blockade, it is possible that the concentration of ICIs or the dosing regimen we used was not optimal for blockade of both PD-L1 and CTLA-4 in these tumor models, thus further studies are required." (PMID 38328418, 2024). "The Phase II CheckMate 142 Study combined pembrolizumab and ipilimumab (anti-CTLA4) to demonstrate durable clinical benefit using these immunotherapies as a frontline treatment for MSI-H/dMMR metastatic CRC patients, regardless of baseline demographic and tumour genetics." (PMID 37563222, 2023). "by using TIMER 2.0 online tool and adjusting tumor purity, we found that SPTBN1 expression had negative correlations with the expression levels of TNFSF9 (R =-0.238, p = 2.31E-07), PDCD1 (R =-0.191, p = 3.81E-05) and CTLA4 (R =-0.16, p = 5.67E-04) in KIRC (revised_Figure 6B)." (PMID 37013511, 2023). "In addition, the results show that AU-011 combined with anti-CTLA-4, PD-L1 and LAG-3 with PD-L1, but not LAG-3 alone, is more effective in reducing the total tumor burden and enhancing the survival of animals bearing bilateral tumors than either treatment alone." (PMID 36997666, 2023). "Unlike PD-1 and CTLA-4, VISTA expression is prominent in myeloid cells, including neutrophils and MDSCs, which play a critical role in suppressing tumor-specific T-cell responses; this suggests that VISTA plays a key role in tumor evasion from the immune system." (PMID 36891296, 2023). "To test whether anti-CTLA-4 VHH with or without half-life extender could show therapeutic effects in different syngeneic models, we evaluated anti-tumor effects of H11 and H11-HLE in MC38 and H22 tumor-bearing C57BL/6 mice and BALB/c mice, respectively." (PMID 35237846, 2022). "In addition, immune checkpoint-related molecules – PD-L1, CTLA-4, PD-1, and TIGIT – are more highly expressed in normal (but not tumor) lung tissues; these molecules might dampen immune response to either viruses or cancer." (PMID 36324736, 2022). "PD-1, CTLA4, LAG3, TIGIT, and TIM-3 (HAVCR2) are known as inhibitory molecules expressed in exhausted T cells that have an impaired ability to kill tumors because they neither respond to T cell receptor stimulation nor secrete anti-tumor cytokines such as interferon γ and tumor necrosis factor-α." (PMID 35480109, 2022). "Similarly, the treatment with anti-CTLA-4 mAb in a preclinical model of HNSCC that recapitulates the tobacco-related molecular profile showed complete response and no tumor recurrence accompanied by an increase of CD8+ T-cell infiltration and a reduction in Tregs cell proportion." (PMID 33804419, 2021).
tumor (continued). "Though it has been suggested that the efficacy seen with CTLA-4 inhibitors may be mediated in part through the depletion of Tregs, recent evidence suggests that CTLA-4 inhibitors do not significantly change or deplete Tregs within the tumor microenvironment." (PMID 34141625, 2021). "Notably, we observed that patients with high EMP3 expression also had high expression of the immune checkpoints PD1/PDL1 and CTLA4, which may explain why immune activation was enriched in the EMP3 high subgroup, but did not hinder tumor progression." (PMID 34268874, 2021). "Moreover, CTLA-4 blockade enhanced the infiltration of eosinophils (CD45+, CD11b+, CD11c−, Ly6G−, SSChi) into tumors, regardless of CD80 expression on tumor cells, and increased the frequency of MHC-II− M2 macrophages within the subpopulation of TAMs in TC-1-induced tumors." (PMID 33923750, 2021). "Although the basis for the negative correlation of CTLA-4 expression to prognosis was not determined in the relevant studies, it is possible (perhaps even probable) that such poor prognoses were mediated by the direct suppression of immune effector cell function by CTLA4+ tumor tissue." (PMID 33384695, 2020). "Targeting CTLA-4 and PD-1 non-redundantly mobilizes and activates alternate T cell components, with CTLA-4 shown to inhibit priming and generation of antigen-specific T cells in the lymph nodes whereas PD-1 limits CD8+ T cell numbers in the tissue, for superior anti-tumor outcomes." (PMID 32849557, 2020). "To reinvigorate CTLA-4-targeted immunotherapy, we and others have reported that rather than blocking CTLA-4 interaction with its cognate targets, CD80 and CD86, anti-CTLA-4 antibodies achieve their therapeutic responses through selective depletion of regulatory T cells in the tumor microenvironment." (PMID 31991588, 2020). "In contrast to previously published findings with other tumor models, we did not observe a significant difference in tumor growth in JAX mice compared to TAC mice of untreated 9464D-GD2 tumors or tumors treated with RT alone or RT and combined 1⁄2 dose IT-IC, anti-CTLA-4, CpG, and anti-CD40." (PMID 31810498, 2019). "Polymerase chain reaction (PCR)-analysis on CT26 tumor tissues from BALB/c and T cell lacking BALB/c nu/nu indicated that the CTLA-4 expression was T cell dependent and therefore the tracer could be used to image CTLA-4 positive T cells." (PMID 31696402, 2019). "Although current clinical CTLA-4 antibodies do not efficiently deplete Tregs from solid tumors, development of 2nd generation CTLA-4 antibodies for patients that can kill Tregs either systemically or specifically in the tumor microenvironment are nearing the clinic." (PMID 31771649, 2019). "These signatures indicate an immunologically active tumor, or “hot tumor,” and all patients with complete response or partial response in the anti-CTLA-4-resistant group had the “hot tumor” signature, although not all responders in the anti-CTLA-4-naïve group had the “hot tumor” signature." (PMID 29896449, 2018). "Selumetinib, whether as monotherapy or in combination with anti-CLTA-4, did not change the percentage of IFNγ-producing T-cells within total splenocytes and tumor samples, following ex-vivo stimulation with anti-CD3, when compared to control or anti-CTLA-4 antibody alone (data not shown)." (PMID 28807001, 2017). "In contrast to 4T1 tumor cells, which did not markedly express B7-1 and PD-L1, CT26 tumor cells expressed a low level of PD-L1 but a high level of B7-1 (see Results); hence their practicability for immune checkpoint combination therapy, specifically with anti-CTLA-4." (PMID 26910920, 2016). "However, since the combined ICI treatment could not improve tumor cell recognition by peptide-stimulated T cells, we assume that for these two MSI CRC cases, immunosuppression does not only depend on PD-1, PD-L1 and CTLA4." (PMID 39075115, 2024).
tumor (continued). "Similarly, the administration of single-agent anti-CTLA4 (median time to endpoint: IgG 12 days, anti-CTLA4 11 days) and anti-PDL2 (median time to endpoint: IgG 14 days, anti-PDL2 13.5 days) did not achieve significant a tumor growth delay compared to their respective isotype controls." (PMID 39199612, 2024). "In addition to conventional anti-PD-1/PD-L1 therapy, anti-CTLA-4 therapy, CAR-T therapy, etc., immunotherapy can also be induced by stimulating the maturation of immune cells or inhibiting negative immune cells, regulating the tumor immune microenvironment and cancer vaccines." (PMID 35524277, 2022). "In addition, a recent study performing single cell analyses of the tumor and the microenvironment in primary and metastatic UMs outlined genomic complexity, as well as revealing a different subset of CD8+ T cells expressing checkpoint marker LAG3 but not PD1 or CTLA4." (PMID 36497441, 2022). "Whether VISTA, CTLA-4, TIM-3, and other immune regulators suppresses CD8+ T cell cytotoxic killing in our system is unknown but represents a promising avenue for future research that could explain why PD-1/PD-L1 interactions do not suppress tumor CD8+ T cell killing in our system." (PMID 33968059, 2021). "However, immune checkpoint inhibitors such as anti‐CTLA‐4 and anti‐PD‐1 antibodies have had little success as monotherapies in the treatment of GBM, suggesting that blockade of immune checkpoints alone is not sufficient to restore anti‐tumour immune functions in the GBM TME." (PMID 32567735, 2020). "However, a-CTLA-4 fails to counteract autocrine/paracrine TGFβ signaling, thereby resulting in NFAT/SMAD3-mediated upregulation of FOXP319 and a paradoxical increase in tumor-infiltrating Tregs in the TGFβ-enriched immune microenvironment found in the majority of cancers." (PMID 29467463, 2018). "Interestingly, although tumor infiltrating SKAP55 KO or ADAP KO CD8+ T cells, as well as CD4+ effector/memory T cells, substantially reduced PD-1 expression during anti-tumor response, we did not observe any significant changes in CTLA-4 expression or infiltrating CD4+Foxp3+ Tregs in vivo." (PMID 25851535, 2015). "It is reasonable to suspect that Tregs expressing CTLA-4 in the tumor microenvironment could similarly modulate DCs that infiltrate the tumor, however, definitive evidence that CTLA-4 participates in Treg-mediated suppression in the tumor microenvironment is lacking." (PMID 23087904, 2012).
cancer (4,735 papers, 2007 to 2026). A tumor composed of atypical neoplastic, often pleomorphic cells that invade other tissues. "Immune checkpoints such as cytotoxic T-lymphocyte-associated protein 4 (CTLA-4), programmed cell death 1 (PD-1), and programmed cell death ligand 1 (PD-L1) have been targeted in cancer therapy, however, the efficacy of these interventions remains limited." (PMID 41639053, 2026). "Immune checkpoint inhibitors (ICIs) have transformed cancer therapy by enhancing antitumor immune responses, including agents targeting cytotoxic T-lymphocyte-associated antigen 4 (CTLA-4), programmed cell death protein 1 (PD-1), and its ligand (PD-L1)." (PMID 41517602, 2026). "High ICOS expression was present in 14% of cancers and was independently associated with high PD‐1, PD‐L1, and CTLA‐4 expression." (PMID 41474629, 2026). "In this context, two key molecular drivers of cancer immune-suppression have been identified: the cytotoxic T lymphocyte-associated protein 4 (CTLA4) and programmed cell death 1 (PD1)." (PMID 40230698, 2025). "In turn, the C-allele, which causes higher expression of the CTLA-4 molecule, confers an increased risk of cancer development." (PMID 41141615, 2025). "A low NLR has been found to be associated with irAE incidence and improved cancer outcomes in PD-1/PD-L1-treated patients, but less has been published on CTLA-4-treated patients." (PMID 40563660, 2025). "Based on previously published data showing an association between irAEs and improved cancer outcomes in the PD-1/PD-L1 blockade, we first looked at this association in our population of CTLA-4 ICI-treated patients." (PMID 40563660, 2025). "Specifically, TIM-3 and CTLA-4 overexpression has been implicated in T cell exhaustion, contributing to the immune escape of cancer cells." (PMID 40264779, 2025). "Immune checkpoint inhibitors (ICIs) targeting programmed cell death-1 (PD-1), programmed death ligand-1 (PD-L1), and cytotoxic T-lymphocyte-associated protein 4 (CTLA-4) have revolutionized cancer therapy by restoring antitumor immunity." (PMID 41463041, 2025). "As discussed in Section 6, while immune checkpoint inhibitors targeting PD-L1 and CTLA-4 have transformed cancer immunotherapy, they can cause immune-related adverse effects like fatigue, skin rashes, endocrine disorders, and hepatic toxicities." (PMID 41208998, 2025). "SNPs in key immune checkpoint genes such as CTLA-4, PD-1, and PD-L1 have emerged as promising biomarkers for predicting both cancer susceptibility and the efficacy of immunotherapy." (PMID 41244914, 2025). "TMB and CYT is significantly associated with significant pan-cancer survival benefits and is effective for anti-CTLA-4 and anti-PD-L1 immunotherapy." (PMID 41174058, 2025). "Cancer immunotherapies that target the immunosuppressive checkpoint receptors cytotoxic T-lymphocyte-associated protein 4 (CTLA4) or PD-1 and its ligand PD-L1, have changed the landscape of anticancer immunotherapy." (PMID 40725123, 2025). "By expressing some ligands on their surface, such as cytotoxic T‐lymphocyte‐associated antigen 4 (CTLA‐4) or PD‐L1, cancer cells can maintain T cells in an inactive state." (PMID 38775116, 2025). "In humans, hepatic lesions can be induced by anti-cancer immunotherapy (anti-PD-1 and anti-CTLA-4) and are associated with a predominant CD8 T cell infiltrate in the lobular zone, suggesting a reactivation of the local liver-antigen-specific T cell response." (PMID 39880819, 2025). "The number of synergistic genes associated with classical ICPs (PD-1, PD-L1, CTLA-4) across different cancers and modules was also compared." (PMID 40728857, 2025). "Findings suggest that specific SNPs in the CTLA-4, PD-1, and PD-L1 genes influence both treatment outcomes and the risk of immune-related adverse events across various cancers." (PMID 41244914, 2025).